TNF (tumor necrosis factor)
Diseases named in the same sentence as TNF in open-access papers (continued):
Sharing a sentence is not in itself a finding about the gene and the disease.
tumor (continued). "In immune‐intact mice CDXs, apart from inhibiting tumor growth, ANO1 knockdown also increased the anti‐tumor immune activity, marked by increased infiltration/expression of CD8+ T cells/IFN‐γ/TNF‐α/granzyme B/IL‐13 and reduced PD‐L1 expression." (PMID 37341301, 2023). "Tumor-infiltrating T-helper 1 cells can induce senescence in tumor cells through secretion of the cytokines IFN-γ and tumor necrosis factor (TNF)." (PMID 36980745, 2023). "The prominent role of IFNα/β, IFNγ and TNFα pathways in the induction of antigen processing and MHC-I-mediated antigen presentation on tumor cells prompted us to test H2Kb-OVA expression in CTRL and Adam2 O/E cells in response to IFNβ, IFNγ and TNFα treatment." (PMID 37258521, 2023). "One study has shown that exosomes released by dendritic cells carry tumor necrosis factor (TNF) and TNF-related apoptosis-inducing ligand (TRAIL), which bind to the TNF receptors on tumor cells and activate caspases, eventually resulting in apoptosis." (PMID 37895415, 2023). "DC101 can decrease the high expression of VEGF after VDA therapy; temporarily normalize tumor blood vessels; increase the number of CD8+ T cells within the tumor; and significantly increase the levels of IFN-γ, TNF-α, and IL-2 after treatment." (PMID 37111692, 2023). "In mice with allogenic Lewis lung carcinoma treated with LRT, there were increases in TNFα and TRAIL after partial irradiation, correlating with tumor growth inhibition." (PMID 37979032, 2023). "Both mCAF and SPP1+ TAMs were mainly enriched in tumor tissues, and in many identical cancer hallmarks, such as EMT, angiogenesis, TGF-β, IL-6/JAK-STAT3, and TNF-α/NF-κB signaling pathways." (PMID 37853464, 2023). "An NKCE incorporating the Nkp30-specific ligand, B7-H6, can adequately activate NK cells and direct them towards tumor cells, leading to the secretion of IFN-γ and TNF-α." (PMID 37638058, 2023). "When administered to mice, the complex inhibited tumor growth, reduced signs of general toxicity, neurotoxicity and cardiotoxicity, increased the immune response (serum levels of IFN-γ, TNF-α and chemokines CCL4 and CCL17) and prolonged animal survival." (PMID 36672622, 2023). "Some like members of the tumor necrosis factor (TNF)-family like FAS ligand (FASL), TNF and TNF-related apoptosis inducing ligand (TRAIL) can induce tumor-cell apoptosis upon the formation of immune synapses." (PMID 36899361, 2023). "Teff cells directly kill tumor cells by inducing apoptosis and secreting cytokines, such as interferon-γ (IFN-γ) and TNF-α, and CD4+conv cells mainly exert an indirect antitumor effect by assisting Teff cells." (PMID 37064872, 2023). "Anyway, we can learn more from the expression characteristics of Tim-3, TNF-α, and IFN-γ that the potential mechanism of them in the immune system against tumor." (PMID 36865498, 2023). "Secretion of VEGFC can induce lymphangiogenesis, while increased CCL5 in tumor microenvironment can form a concentration gradient to recruit M2 TAM, then promote TNF‐α secretion to increase lymphatic permeability." (PMID 37409440, 2023). "The microbial metabolite TMAO promoted infiltration of TAMs, increased the proportion of TNF‐α+ IFN‐γ + T cells in the tumour tissues and inhibited tumour growth." (PMID 38082435, 2023). "Multiple investigations have demonstrated that CXCR4, TNF-α, and TGF-β play a role in regulating drug resistance in MSC located in the tumor environment." (PMID 36966336, 2023). "Promoting the T‐cell proliferation and secretion of cytokines TNF‐α and IFN‐γ can effectively promote the capacity of CD8+ T cells to kill tumor cells and elevate CD8+ T‐cell immune response against tumors." (PMID 37506147, 2023). "TNF (p = 0.0284), PPARG (p = 0.0379) and ESR1 (p = 0.0268) were significant in tumor staging in GC patients." (PMID 37171392, 2023). "After making contact with tumor-cell-surface antigens, CAR-Ts activate and produce cytokines, including IFN-γ, TNF-α, and IL-2." (PMID 37298069, 2023).
tumor (continued). "The tumor cells of iCCA shared common activated signaling pathways, including IL-6/STAT3, Wnt, transforming growth factor (TGF), and tumor necrosis factor (TNF)." (PMID 36980203, 2023). "Adoptive transfer of CD62L+CD44− naïve OT1 CD8+ T cells to Tipe2ΔNK/ΔNK mice or control mice bearing MC38‐OVA tumors showed that donor‐derived tumor‐infiltrating OT1 CD8+ T cells in Tipe2ΔNK/ΔNK mice expressed higher levels of IFN‐γ and TNF‐α." (PMID 36807566, 2023). "In this model, the tumor cells transferred cGAMP via gap junctions (CX43) to astrocytes which led to astrocyte-driven production of IFN-α and TNF-α driving the growth and chemoresistance of the invading tumor." (PMID 37287967, 2023). "TNF-α can exert opposing effects on MSCs, from inducing MSC apoptosis to enhancing their anti-tumor capacity." (PMID 36814921, 2023). "After a literature review, we collect factors that directly regulate the function of NK cells, and the gene list is IL2, IL15, IL18, IL21, all of which promote NK cell-mediated tumor death, while IL6, TGFβ and TNFα promote NK cell exhaustion." (PMID 38159250, 2023). "CD8+ T cells are cytotoxic lymphocytes; their tumor–antigen interaction is through the production of IFN-γ, tumor necrosis factor α, granulocyte colony-stimulating factor, and other cytokines directly or indirectly lyse tumor cells." (PMID 37512088, 2023). "Tumor necrosis factor (TNF-α), a widely known inflammatory factor, plays an important role in the tumor microenvironment." (PMID 37063424, 2023). "Modified exosomes that carry Tumor Necrosis Factor (TNF)-related Apoptosis-inducing Ligand (TRAIL) induce apoptosis in cancer cells, thereby decreasing tumor growth." (PMID 38188673, 2023). "CAAs release chemicals such as CCL2, CCL5, IL-1β, IL-6, TNF-α, VEGF, and leptin, facilitating tumor spread and evading the immune system." (PMID 38068912, 2023). "By contrast, tumour necrosis actor α (TNFα) was decreased in the former, while levels of interleukin 12p70 (IL12p70) and interleukin 23 (IL23) were reduced in gas plasma-treated RE tumours." (PMID 37460712, 2023). "Several factors secreted by tumor cells, such as granulocyte-colony stimulating factor (G-CSF), macrophage migration inhibitory factor (MIF), TNF-α, and autophagosomes (TRAPs), have been shown to upregulate PD-L1 expression on macrophages." (PMID 37313405, 2023). "The consequence is a decrease in TNF-α and IFN-γ expression, leading to reduced CD8 + T cell counts and tumor immune evasion." (PMID 38087360, 2023). "On the other hand, the last two types of cells are mainly distributed in infection and tumor sites, performing direct effector functions such as secretion of cytokine IFN-γ and tumor necrosis factor-α (TNF-α), as well as cytotoxicity." (PMID 37597083, 2023). "The administration of TNFα for the treatment of CT26 tumors affects tumor cell growth in vitro and tumor growth in vivo (subcutaneous transplantation)." (PMID 36996146, 2023). "In PDAC xenograft immunodeficient mice, Ad-TNF-α-IL-2 boosted both CAR T-cell and host T-cell infiltration to the tumor site and changed host tumor immunological condition with M1 polarization of macrophages and augmented dendritic cell maturation." (PMID 37020537, 2023). "REP TILs were able to respond to activation in the presence of tumor cells; increases in the CD3+ (median 0.72% vs. 1.33%, P = 0.098) and CD4+ (0.46% vs. 1.08%, P = 0.012) T cell IFNγ and TNFα expressions were observed after 6 hours of co-culture." (PMID 37484198, 2023). "Recent studies have shown that pro-inflammatory cytokines such as interleukin (IL)-1β, tumor necrosis factor (TNF)-α, and IL-6 in a tumor microenvironment contribute to the development and metastasis of cancers through the immune escape of cells [2, -4]." (PMID 37501379, 2023). "The IFN- signaling pathway stimulates the production of IL12, ICAM1, and tumor necrosis factor (TNF), all of which are deadly to tumor cells and suppress tumor development." (PMID 37728418, 2023).
tumor (continued). "M1 macrophages also produce high levels of IL-12, IL-1, IL-23, TNF-α, CXCL10, and nitric oxide synthase (iNOS), which play important roles in the inhibition and killing of tumor cells." (PMID 37153586, 2023). "Moreover, cytokines such as IL-1β and TNF-α have also been reported to be inducers of the inflammatory phenotype in CAFs48, which in turn upregulate the expression of cytokines and chemokines that may further promote tumor growth and proliferation." (PMID 37863888, 2023). "Numerous studies have shown that ILC1s exert a tumor-inhibiting effect by secreting the tumor-killing factors IFN-γ and TNF-α." (PMID 37679802, 2023). "On the other hand, PGE2 from tumor cells triggers the nuclear p50/NF-κB signaling in M-MDSCs, which reprograms their response to IFN-γ and decreases TNF-α generation." (PMID 38008741, 2023). "Th1-polarized CD4+ cells, on the other hand, promote macrophage cytotoxicity by secreting cytokines such as TNF, which binds cytotoxic CD8+ T cells that have anti-tumor effects in vivo." (PMID 37225919, 2023). "Studies have shown that immune factors such as TNF and IFN can not only directly kill tumor cells but also restrain the formation of blood vessels, thus inhibiting tumor growth." (PMID 37049720, 2023). "The expression levels of TNF-α, IL-6 and VEGF were all increased in patients with tumor length > 5 cm compared with patients with tumor length ≤ 5 cm, and the differences were all statistically significant (all P < 0.001)." (PMID 37430251, 2023). "Mice treated with PBS and LNPs alone had similar concentrations of TNF-α and IFN-γ in serum and tumor, while the concentrations of cytokines significantly increased in mice with GSDMBNT mRNA@LNP treatments." (PMID 37454146, 2023). "The results showed that Focal adhesion, TNF signaling pathway, ECM−receptor interaction in the C2 subtype adhered to cells and migrated and the path expression of tumor invasion had a rise." (PMID 36819132, 2023). "Assessment of peripheral cytokines in both MC38 and EMT6 tumor models revealed that the combination treatment with docetaxel + NHS-IL-12 yielded increased levels of the proinflammatory cytokines IFNγ, IL-12, and tumor necrosis factor α (TNFα)." (PMID 37166485, 2023). "Tumor-promoting cytokines are IL-6, transforming growth factor (TGF-β), TNF-α, and IL-23, they activate STAT proteins, suppress apoptosis, and contribute to EMT." (PMID 37298889, 2023). "CD8+ T cells inhibit tumor growth by secreting cytokines, such as interferon (IFN)-γ, granzyme B, and tumor necrosis factor-α (TNFα)." (PMID 37901252, 2023). "In response to lipopolysaccharide (LPS), TNF-α, and IFN-γ, TAMs can polarize into either the M1 phenotype, which has pro-inflammatory and anti-tumor activities, or the M2 phenotype, which has pro-tumor activities." (PMID 37465670, 2023). "Relative vessels number, necrosis areas and Ki-67 index were assessed microscopically; tumor volumes were determined by 3D reconstruction from histological images; serum levels of HIF-1α, IL-1β, and TNFα were determined by ELISA." (PMID 37542119, 2023). "Both are known to produce cytokines, such as tumor necrosis factor (TNF)-α, interleukin 1 (IL1), and interleukin 6 (IL6), which can impact GBM cell behavior and contribute to tumor growth, angiogenesis, and invasion." (PMID 37345035, 2023). "The ratio of TNFα+ CD4+ and IL-17A+ CD4+ was also skewed towards more IL17A+ CD4+ in tumor compared with STM." (PMID 38074634, 2023). "A recent study revealed that upon TNF-α treatment, the active caspase-8 cleaves GSDMC, which unleashes the pore-forming GSDMC-NT to trigger pyroptosis in tumor cells." (PMID 36742298, 2023). "On their arrival to the tumor site NK cells get activated by soluble (e.g. IL-2, IL-15, TNF-α, and IFN-γ) and contact-dependent signals from the tumor microenvironment (TME)." (PMID 37841273, 2023).
tumor (continued). "Lymphocytes, especially tumor-infiltrating lymphocytes, play a pivotal role in antitumor immune effects by triggering cytotoxic cell death and inhibiting tumor proliferation and migration by secreting cytokines such as IFN-γ and TNF-α." (PMID 37046639, 2023). "We induced THP‐1 polarization toward M1‐like macrophages by TNF‐α and subsequently co‐cultured with HCCC9810 to mimic the tumor microenvironment." (PMID 37688511, 2023). "The content of TNF‐α and INF‐γ in tumor tissues also showed that the sgCas9‐AdV/Gel treatment elicited a significant immune response." (PMID 36840638, 2023). "We found that GDF, IGF, OSM, TNF, and TWEAK outgoing signaling pathways were all enriched from SCAMs towards the tumor epithelium." (PMID 37164949, 2023). "The receptor activator of the nuclear factor κB ligand (RANKL) is a homotrimeric transmembrane protein member of the tumor necrosis factor (TNF) cytokine family expressed by osteoblast cells and tumor cells." (PMID 37511127, 2023). "This evidence gives strong evidence that stimulation of the NF-kB signalling pathway, induced by TNF-α, promotes the endosseous invasion of OSCC tumour cells." (PMID 36980727, 2023). "M1 macrophages are referred to as the anti-tumor effector population and are classically activated by interferon-γ (IFN-γ), tumor necrosis factor α (TNF-α), and granulocyte-macrophage colony-stimulating factor (GM-CSF)." (PMID 37876933, 2023). "Recently, a cocktail consisting of TNFα, CD40 agonist and a tumour-specific antibody was shown to increase the ability of neutrophils to kill human tumour cells in vitro." (PMID 37180120, 2023). "In line with previously published CRISPR KO screens in mouse and human tumor cells, we identified genes involved in autophagy, IFN-γ and TNF-α signaling pathway." (PMID 37732732, 2023). "ML NK cells also showed enhanced in vitro production of TNF-α and IFN-γ against different ovarian cancer cell lines, including SKOV-3, MA148, OVCAR5, and A1847, but also controlled the MA148 tumor growth of an in vivo xenogeneic mouse model." (PMID 37205105, 2023). "Furthermore, the release of TNF-α following tumor irradiation may stimulate the activity of Tregs." (PMID 37221555, 2023). "This BsAb can robustly induce cytokines’ (IFN-γ, TNF-α, and IL-2) secretion in T cells and MUC1-expressing tumor cells’ co-culture assay." (PMID 37489369, 2023). "TNF-α, and more importantly IFN-γ, can inhibit tumor growth, metastasis, and angiogenesis, induce M1 macrophage polarization and Treg fragility as well as tumor senescence." (PMID 37587450, 2023). "The M1 macrophages secrete pro-inflammatory cytokines TNF-α, IFN-γ, IL-1β and IL-8 and exert pro-inflammatory and anti-tumor functions." (PMID 36845095, 2023). "TNF-α (also known as TNF), a major pro-inflammatory cytokine primarily produced by activated macrophages, T-lymphocytes, and tumor cells, was involved in the pathological processes of DM and cancer." (PMID 36357631, 2023). "Among these, a crucial role is played by NF-κB, which upregulates several pro-inflammatory genes, including TNFα, IL1, and IL6, but has also been shown to act as a tumor promoter in inflammation-related cancers." (PMID 38247453, 2023). "CTLs are generally regarded as the major executor of antitumor immune response, among which TEMs secret pro-inflammatory cytokines, such as TNF-α and IFN-γ, mediating immediate effector function, thus play an important role in tumor inhibition and killing." (PMID 37700338, 2023). "The authors reported distant tumor inhibition, DCs maturation, high infiltration of CD3+ and CD8+ T cells, increased secretion of INF-γ, and release of TNF-α and IL-6." (PMID 37238966, 2023).
tumor (continued). "TNF-α promotes HNSCC progression by upregulating MMP-9, which in turn enhances tumor migration and invasion by facilitating TGF-β1-induced EMT." (PMID 37711747, 2023). "Studies have shown that in bone marrow chimeras with ATG5-deficient donor cells, there is a significant increase in IFN-γ and TNFα-producing CD8+ T cells in tumor-infiltrating lymphocytes, leading to improved tumor control." (PMID 37675121, 2023). "NK cells are considered a part of the innate immune system and exercise their function through the secretion of perforins, granzymes, TNF-α, and interferon gamma (IFN-γ) leading to tumor cell lysis." (PMID 37174089, 2023). "These cells discharge pro-inflammatory substances such as tumor necrosis factor-α (TNF-α), interferon-γ (IFN-γ), IL-1β, and IL-6, which exacerbate local and systemic inflammation and act as potent tumor promoters." (PMID 37108477, 2023). "Other factors that were shown to be induced by the primary tumor-expressed proteins VEGF, TGF-β, and TNF-α are the inflammatory chemoattractants S100A8 and S100A9." (PMID 37222464, 2023). "We observed that in tumor tissues, the combination treatment [ADU-S100 (20 μg) + CpG ODN (20 μg)] upregulated the expression level of IFN-β, IL-12, and TNF-α in a synergistic manner compared with the other treatments." (PMID 37901237, 2023). "The results of RT-qPCR showed that the expression levels of CCL2, CCL22, TNF-α and IFN-γ in tumor tissues were significantly increased after TCS treatment." (PMID 36674931, 2023). "PTEN mRNA-LNPs reversed the immunosuppressive nature of the tumor microenvironment by promoting CD8+ T cell infiltration and enhancing the expression of proinflammatory cytokines including IL-12, tumor necrosis factor-α (TNF-α), and IFN-γ." (PMID 37805495, 2023). "Critically, however, the NK cells in the TME exhibit an exhausted phenotype that results in decreased TNF-α and IFN-γ production, which effectively reduces their tumor-cell killing capabilities." (PMID 37174089, 2023). "The mo-Macs were predicted to deliver activation signals through the TNFR (TNF-TNFRSF1A), TGFBR (TGFB1-TGFBR2), and EGFR (EREG-EGFR) pathways to tumor cells." (PMID 37187731, 2023). "In co-cultures with CD1d+ tumor cell lines, the CD1d-Vδ2 bsTCE triggered type 1 NKT cells to secrete Th1 and Th2-type cytokines, including IL-2, IL-4, tumor necrosis factor (TNF), and interferon (IFN)-γ, whereas Vγ9Vδ2-T cells mainly secreted TNF and IFN-γ." (PMID 36868236, 2023). "In this context, the levels of GM‐CSF, TNF‐α, IFN‐γ, IL‐1β, IL‐2, IL‐4, IL‐6, IL‐10, and IL‐13 in the peripheral blood of H22 tumor‐bearing mice were detected." (PMID 36043445, 2023). "Permanently produced low-dose TNF-α enhances tumor formation, growth, metastasizing and cachexia, while supra-physiological dosages of TNF-α can destroy tumor vascularity and induce necrosis and apoptosis in tumor cells." (PMID 37610672, 2023). "However, mild hyperthermia significantly enhanced the efficacy of immunotherapy and reduced the risk of cancer metastasis in mouse models of pancreatic cancer, which may contribute to increasing drug accumulation and improving the anti-tumor immune activity with increased secretion of TNF-α." (PMID 36765695, 2023). "Lmo@RBC-induced GSDMC-mediated cancer cell pyroptosis promoted the secretion of IL-6, TNF-α, and IFN-γ of bone marrow–derived DC and accumulation of DC and CD8+ T cells in tumor tissues." (PMID 35739593, 2022). "Subsequently, neutrophils increase the number of CD8+, CD4+T cells, and B cells in the tumor and promote the release of IFN-γ, TNF-α, and IL-12; thus, the antitumor immunity and anticancer effect was enhanced." (PMID 36034656, 2022). "After extracting TAMs from mouse-bearing tumor tissue, we found that IL-10 and TGF-β was upregulated and TNF- α was downregulated in the silent ALKBH5 group." (PMID 35982895, 2022).